AQP4 (aquaporin 4)
Diseases named in the same sentence as AQP4 in open-access papers (continued):
Sharing a sentence is not in itself a finding about the gene and the disease.
depression (continued). "In our study, 46% of patients with AQP4-ON were considered positive for depression based on the BDI-II." (PMID 37840923, 2023). "In conclusion, we report a new mechanism whereby melatonin improves depression outcomes by regulating the expression of the circadian protein Per2, maintaining the circadian rhythm of astrocytic AQP4 polarization, and restoring glymphatic function." (PMID 37802998, 2023). "To determine if melatonin protected CUMS mice from depression-like behaviors via AQP4, we pharmacologically blocked AQP4 with TGN020." (PMID 37802998, 2023). "Remarkably, electroconvulsive therapy was able to suppress depression-like behaviors and increased the extent of AQP-4 immunoreactive processes around blood vessels in the rat genetic model." (PMID 35530179, 2022). "AQP4 was predicted to be inhibited by hsa-miR-320a, which is increased by depression in AD patients." (PMID 36040555, 2022). "Reactive astrocyte proliferation and changes in AQP4 expression are common in postmortem tissues from patients with depression, but the related experiments have produced contradictory results." (PMID 35547631, 2022). "In a postmortem study, patients with depression exhibited lower AQP4 mRNA and protein expression in the brain than healthy control." (PMID 35164330, 2022). "Recently, it has been found that CUMS-induced NE release can decrease the polarization of AQP4 expression in astrocytes, inhibiting the function of the glymphatic system and inducing oxidative stress and inflammation, leading to depression-like symptoms." (PMID 36421482, 2022). "For example, AQP-4 knockout mice displayed both corticosterone-induced depression and defective memory, symptoms reversed by mifepristone and fluoxetine, linking the brain water circulation to SRDs." (PMID 34776871, 2021). "Recent studies indicate that the therapeutic option for depression is via the restoration of astrocytes function, AQP4, and glymphatic system, which provide further supporting evidence for the critical role of glymphatic flow in depression." (PMID 34025481, 2021). "The expression of aquaporin‐4 (AQP4), a principle water channels in the brain that is expressed mainly by astrocytes, was reduced in patients with depression." (PMID 32920880, 2021). "Decreased astrocytes and downregulated AQP4 expression have been reported in various animal models of depression, supporting dysfunctional glymphatic transport in depression." (PMID 34025481, 2021). "The effect of early initiation of relapse preventive therapies other than oral PSL to prevent the progression of depression and fatigue in AQP4-IgG-positive NMOSD remains to be confirmed by future studies." (PMID 33692739, 2021). "During the neuroinflammatory response, reactive astrocytosis, and AQP4 depolarization have been widely reported in depression." (PMID 34025481, 2021). "Our findings on univariable analysis in both AQP4‐Ab and MOG‐Ab patients are in agreement with this observation, although on multivariable analysis, depression remained a significant independent variable only within AQP4‐Ab patients." (PMID 32187851, 2020). "Replication steps including non-European cohorts are needed to confirm this finding and establish the functional role of the AQP4 locus in the etiopathology of depression in CAD patients." (PMID 30563176, 2018). "We therefore propose AQP4 as a promising node for therapeutic intervention, whose modulation may help counteract core pathophysiological processes in depression, offering a potential avenue for novel treatment development." (PMID 41683659, 2026). "Additionally, the presence of AQP4 autoantibodies in some individuals with treatment-resistant depression suggests a potential autoimmune component." (PMID 40725164, 2025).
depression (continued). "Furthermore, an immune-related model of depression by intracerebroventricular injection of the tumor necrosis factor (TNF)-like weak inducer of apoptosis (TWEAK) significantly decreased AQP4 protein expression and increased anhedonic behaviour." (PMID 40650814, 2025). "Interestingly, in a genetic rat model for depression-like behaviors, AQP-4-positive astrocyte endfeet were also found to be reduced when compared with Wistar rats." (PMID 35530179, 2022). "In the prefrontal cortex of human subjects with depression, the coverage of vessels by the aquaporin 4 (AQP-4)-immunoreactive endfeet of astrocytes is significantly reduced, even if the extent of those feet is not changed when labeled for the cytoskeletal protein GFAP." (PMID 35530179, 2022). "However, emerging animal studies provide powerful evidence implying the pathological alterations of astrocytes and AQP4 in depression." (PMID 34025481, 2021). "Within AQP4‐Ab patients, age (P = 0.002), disease duration (P = 0.004), number of clinical attacks (P = 0.001), disability (P = 0.007), pain interference (P < 0.001), anxiety (P = 0.026), and depression (P < 0.001) were significant independent variables." (PMID 32187851, 2020). "Within AQP4‐Ab patients, while the relationship of pain, disability, age, disease duration, and number of clinical attacks with fatigue is clear, this is less so for anxiety and depression." (PMID 32187851, 2020). "Additionally, AQP4 has been shown to play an important role in adult neural stem cell proliferation, which is downregulated in depression." (PMID 30563176, 2018). "Similarly, human post mortem studies have shown reduced AQP4 expression in brains of patients with depression, some suggesting that AQP4 autoantibodies might contribute to an immune‐mediated mechanism." (PMID 40329616, 2025). "Furthermore, chronic stress, a major contributor to depression, has been shown to increase AQP4 expression in the hippocampus, whereas its downregulation has been associated with reduced depressive-like behavior, potentially through modulation of NMDA receptor activity." (PMID 40725164, 2025). "The expression of messenger RNA (mRNA) transcripts involved in AQP4 expression in MDD patients is down-regulated, and even the pathological conditions of depression may increase the risk of Alzheimer’s disease development through the impairment of glial lymphatic pathway function." (PMID 37065890, 2023). "Based on our finding that variant rs528732638 which belongs to a LD block with eQTL effects on AQP4 is associated with depression in CAD patients, we speculate that AQP4 may play a role in the etiopathology of vascular depression via promotion of ischemic cytotoxicity." (PMID 30563176, 2018). "Therefore, we hypothesized that expression of reactive astrocytes, activated microglia, glial MT-I/II, and AQP4 would be altered in the hippocampal formation of MTLE patients with major depression and interictal psychosis." (PMID 25889039, 2015). "Similar trends were observed in the brains of patients with major depressive disorder (MDD), with AQP4 expression found to be downregulated in the locus coeruleus and hippocampus." (PMID 37760916, 2023). "AQP4 knockout also revealed negative effects on neuroprotective markers and behavioral outcomes and was associated with increases in inflammatory markers in animal models of depression, indicating that AQP4 exhibits neuroprotective functions in the CNS and against MDD." (PMID 35164330, 2022). "By contrast, neuropathological studies in specimens from major depression patients indicate reduction in hippocampal glial fibrillary acidic protein (GFAP)-positive astrocytes and of AQP4 and MT-I/II in the frontal cortex." (PMID 25889039, 2015). "Similarly, animal models of depression—such as CMS, chronic corticosterone treatment, and stress-sensitive rat strains—show decreased AQP4 protein levels in multiple brain regions, including the PFC, hippocampus, LC, and choroid plexus." (PMID 41462664, 2025).
depression (continued). "While the studies on pathways of biopterin and acetyl-L-carnitine seem promising to enhance our understanding of major depression and of TRD, others - including aquaporin-4, vascular endothelial growth factor (VEGF), and thyroid-stimulating hormone (TSH) - have yield fewer compelling results." (PMID 37941970, 2023). "Previous clinical studies have revealed that blood mRNA AQP4 expression in patients with depression was not significantly different from that in the controls." (PMID 35164330, 2022). "Using an animal model of depression, rats selectively bred for high anxiety-like behavior (HAB), we confirmed a reduced coverage of BVs in the adult PFC by AQP-4-immunoreactive (AQP-4-IR) astrocyte processes with respect to non-selected Wistar rats (NAB), thereby validating it for our study." (PMID 26869881, 2016). "Interestingly, the expression of astrogliosis markers presented a more complex pattern with GFAP and aquaporin-4 (AQP4) levels being lower in MTLE patients with mental disorders and depression specifically, whereas Metallothioneins I/II (MT-I/II) levels being higher." (PMID 40177583, 2025). "On the other hand, the expansion of PVS, malfunction of MLVs, synaptic impairment and depolarization of AQP4 are significantly affected by non-genetic risk factors, such as aging, sleep disorders, metabolic diseases, cerebrovascular diseases, TBI and depression." (PMID 38270115, 2024). "Overall, this limited evidence seems to suggest AQP4 protein and gene expression levels in the peripheral blood of patients with depression and of healthy individuals differ, indicating that symptoms of ACR-induced neurotoxicity may be related to depression and depressive symptoms." (PMID 35164330, 2022).
brain injury (37 papers, 2013 to 2026). Acute and chronic (see also brain INJURIES, CHRONIC) injuries to the brain, including the cerebral hemispheres, CEREBELLUM, and brain STEM. "The analysis of the literature demonstrated that the most significant markers among the AQPs are as follows: for the brain, AQP4, which is very important in brain trauma and hypoxic damage; AQP3 in the skin lesions caused by various mechanisms; and AQP5 in the diagnosis of drowning." (PMID 38473914, 2024). "The analysis of the literature demonstrated that the most significant markers among the AQPs are AQP4 for the brain, which is very important in brain trauma and hypoxic damage; AQP3 in the skin lesions caused by various mechanisms; and AQP5 in the diagnosis of drowning in lung and kidney samples." (PMID 38473914, 2024). "AQP4, the most abundant aquaporin in the central nervous system, is particularly involved in the regulation of brain edema and the response to traumatic brain injury (TBI), including subdural hematomas (SDH) and acute ischemic stroke (AIS)." (PMID 39768394, 2024). "In SAE and other inflammatory brain injuries, corticosteroids such as dexamethasone can reduce AQP4 expression by modulating inflammatory pathways." (PMID 39768394, 2024). "For instance, the involvement of AQP4 was identified in the pathogenesis of intestinal dysfunction after traumatic brain injury due to regulation of intestinal oedema." (PMID 35582765, 2022). "Further in line with our findings, pharmacological suppression of HIF1A due to 2-methoxyestradiol is known to induce a decline in the expression of AQP4 following traumatic brain injury." (PMID 35764613, 2022). "Some studies have reported that N-methyl-D-aspartate (NMDA) receptor inhibition, catecholamine surge control, cerebral edema inhibition by aquaporin-4, and reduced body temperature were beneficial in patients with brain injury." (PMID 33428685, 2021). "Taken together, the protective effect of MK801 on our brain trauma injury model is at least partly owing to the down-regulation of AQP4." (PMID 30483388, 2018). "AQP4 expression largely normalized 48 h after the blast injury, indicating that cytotoxic edema is an early event in blast-induced brain injury." (PMID 24252631, 2013). "Inhibition of AQP4 expression levels can alleviate blood–brain barrier destruction and astrocytes edema in traumatic brain injury mice, while restoring AQP4 localization at the end of perivascular astrocytes can protect the integrity of the blood–brain barrier." (PMID 37873537, 2023). "Studies have found that glial–lymphatic dysfunction appears after brain trauma, and AQP4 gene knockout further aggravates glial–lymphatic dysfunction post-brain trauma, which is consistent with the effect of AQP4 on the glial–lymphatic system discovered in 2012." (PMID 34220413, 2021). "Taken together, these findings indicate that Shuanghe-tang pretreatment may attenuate BBB dysfunction and edema following ischemic brain injury by promoting increased expression of ZO-1, occludin, and AQP4." (PMID 29599893, 2018). "For instance, in juvenile traumatic brain injury (jTBI) models, elevated levels of AQP4 in the glia limitans appear to counterbalance water accumulation at one- and three-days post-injury (as indicated by higher T2 values), leading to a normalization of both AQP4 and T2 levels by day seven." (PMID 37762642, 2023). "In this review, we present and discuss the findings from clinical and experimental studies on AQP4, AQP2, AQP9, and AQP11 in acute brain injuries." (PMID 40564125, 2025). "Furthermore, AQP4 might be useful for estimating the time of survival in traumatic brain injuries." (PMID 34977094, 2021). "Among them, AQP2, AQP4, AQP9, and AQP11 have been implicated in traumatic and non-traumatic brain injuries." (PMID 40564125, 2025). "Aquaporins, particularly AQP4, are integral to maintaining water homeostasis in the brain but also contribute to the pathophysiology of traumatic and non-traumatic brain injuries." (PMID 40564125, 2025).
brain injury (continued). "A previous study reported that mice lacking AQP-4 were partially protected from brain edema in water intoxication and ischemic brain injury." (PMID 35884712, 2022). "Pretreatment with AQP4 inhibitor TGN-020 significantly reduced focal cerebral ischemia induced brain edema whereas bumetanide was shown to attenuate brain edema after traumatic brain injury." (PMID 29403391, 2018). "Treatment with MK801 or MK801 and NMDA did not significantly alter average levels of AQP4 protein determined by fluorescence staining 24 hr after brain trauma." (PMID 30483388, 2018).
cognitive decline (36 papers, 2018 to 2026). "In patients with AD, the loss of perivascular AQP4 localization is implicated in an increased pathological burden of Aβ and p-tau and cognitive decline early in the illness." (PMID 37024941, 2023). "We observe that reduced frontal cortical perivascular AQP4 localization is associated with local Aβ and p-tau pathology, as well as with cognitive decline early in the course of clinical AD progression." (PMID 35473943, 2022). "This decline in perivascular AQP4 localization was associated with increasing Aβ and neurofibrillary pathological burden, and with cognitive decline prior to dementia onset." (PMID 35473943, 2022). "In humans, genetic variation in AQP4 affects Aβ burden, and AD patients with specific AQP4 single nucleotide polymorphism exhibit a rapidly progressive cognitive decline." (PMID 33670754, 2021). "This haplotype consists of 8 SNPs, including rs335929 implicated in cognitive decline in Alzheimer’s patients and rs162008 demonstrated to reduce AQP4 expression." (PMID 32369477, 2020). "Other noncoding AQP4 SNPs were associated with altered rates of cognitive decline after AD diagnosis." (PMID 33134185, 2020). "In a recent study by Burfeind and colleagues, two of the AQP4 SNPs described in the current study, rs9951307 and rs3875089, were reported to be associated with altered trajectories of cognitive decline." (PMID 29479071, 2018). "Furthermore, SNP in AQP4 has been associated with Aβ accumulation, disease progression, and cognitive decline." (PMID 39397929, 2024). "Variations in the AQP4 gene have been linked with Aβ accumulation, disease stage progression and cognitive decline, suggesting that it could serve as a biomarker to accurately predict disease burden in those within the AD spectrum." (PMID 37508938, 2023). "AQP4 genetic variation was associated with Aβ accumulation, disease stage progression, and cognitive decline and could be considered a useful potential biomarker in predicting disease burden for those in the spectrum of AD." (PMID 36140362, 2022). "Although a recent genetic study has shown associations between different AQP4 polymorphisms and varying rate of cognitive decline in PD, further work is vital to determine if a strong link exists between glymphatic dysfunction and the pathogenesis of the human disease." (PMID 36361716, 2022). "Another recent study on Parkinson’s disease demonstrated that specific mutations in AQP4 were likely the cause of sleep disturbance and may act as a prognostic marker for cognitive decline." (PMID 36330347, 2022). "We examined whether AQP4 SNPs were associated with an altered rate of motor or cognitive decline using linear mixed model and Cox regression." (PMID 35356146, 2021). "A widespread loss of AQP4 polarization and overall dysfunction in waste clearance has been found in the aging brain and this reduction in glymphatic clearance has been proposed to contribute to the cognitive decline seen among the elderly." (PMID 32973489, 2020). "Because Aqp4 deletion promotes Aβ deposition, proposed to be an early event in the Alzheimer’s pathological cascade, we evaluated whether changes in perivascular AQP4 localization were associated with cognitive decline prior to the development of frank dementia." (PMID 35473943, 2022). "AQP‐4 dysfunction plays a pivotal role in glymphatic impairment, as demonstrated by animal models where AQP‐4 deletion exacerbates cognitive decline, beta‐amyloid accumulation, and alpha‐synuclein aggregation." (PMID 40376934, 2025). "Aging, chronic inflammation, and neurodegeneration can disrupt perivascular AQP4 localization, leading to neurotoxic protein accumulation (e.g., Aβ, phosphorylated tau), neuroinflammation, and cognitive decline." (PMID 40822471, 2025). "NMO is driven by autoantibodies targeting the astrocyte protein aquaporin-4 (AQP4), leading to vision loss, motor deficits, and cognitive decline." (PMID 39827337, 2025).